CHI3L1 (chitinase 3 like 1)
Diseases named in the same sentence as CHI3L1 in open-access papers (continued):
Sharing a sentence is not in itself a finding about the gene and the disease.
glioma (continued). "In our exploration of EMP3 and CHI3L1, we discovered that both proteins are upregulated in malignant tumors such as glioma and are involved in tumor progression through the PI3K/AKT pathway." (PMID 37887529, 2023). "Reflections on all-grade glioma patients showed that EMP3 and CHI3L1 showed significant differences in the expression of low-grade and high-grade gliomas." (PMID 37887529, 2023). "We found that the expression levels of EMP3 and CHI3L1 were higher in low-grade and high-grade gliomas than in normal brain tissue, and that the levels of EMP3 and CHI3L1 were much higher in high-grade gliomas than in normal brain tissue." (PMID 37887529, 2023). "The 95% CI of age, WHO grade, and CHI3L1 were all on the right side of one (p < 0.05), and these three factors affected the overall survival of glioma patients." (PMID 37887529, 2023). "In conclusion, the average expression levels of EMP3 and CHI3L1 were statistically significant among the eight clinical characteristics of glioma patients." (PMID 37887529, 2023). "In our study, we combined EMP3 and CHI3L1, which are correlated in glioma cells and can be combined as prognostic factors for patients with low-grade glioma." (PMID 37887529, 2023). "We pooled and analyzed the genetic information of 693 glioma patient samples from the CGGA database and found that the mutation rates of EMP3 and CHI3L1 were 1% and 1.2% in 693 patients." (PMID 37887529, 2023). "Based on the TCGA database, we analyzed the influence of gene changes affecting EMP3 and CHI3L1 expression in glioma patients on the survival time of glioma patients." (PMID 37887529, 2023). "The results indicate that a low expression of EMP3 and CHI3L1 significantly affects patients with low-grade gliomas, showing a better prognosis." (PMID 37887529, 2023). "We used TCGA and CGGA databases to analyze the effect of EMP3 and CHI3L1 expression on the prognosis of glioma patients and their correlation with gene expression using bioinformation analysis." (PMID 37887529, 2023). "YKL40 (also known as CHI3L1) has been described as having an important role in glioma cell proliferation." (PMID 37190125, 2023). "The results showed that EMP3 positively correlated with CHI3L1 in both primary and recurrent gliomas." (PMID 37887529, 2023). "In previous studies, EMP3 and CHI3L1 were identified as novel independent predictors of clinical diagnosis, prognosis, and immune infiltration in glioma patients, respectively." (PMID 37887529, 2023). "Results: low-grade glioma patients with a low expression of EMP3/CHI3L1 had a better prognosis, and the combination of EMP3/CHI3L1 is a new predictor for glioma patients." (PMID 37887529, 2023). "To further verify the correlation between EMP3 and CHI3L1 in patients with glioma, we analyzed the correlation between these two proteins in patients with primary and recurrent gliomas." (PMID 37887529, 2023). "To investigate the expression levels of EMP3 and CHI3L1 in different tissues, we analyzed the mRNA levels of EMP3 and CHI3L1 in normal brain tissue, low-grade gliomas, and high-grade gliomas." (PMID 37887529, 2023). "Immunoblot analysis with antibodies specifically recognizing mesenchymal markers demonstrated elevated CD44 levels in all tested glioma cell cultures, whereas high expression of CHI3L1/YKL40 was found only in WG4 and WG14 cells." (PMID 36900355, 2023). "According to these results, the expression levels of EMP3 and CHI3L1 are significant in the prognostic prediction of both primary and recurrent gliomas." (PMID 37887529, 2023). "For example, CHI3L1(Alias symbols: YKL-40) was highly differentially expressed in high-grade glioma (HGG) tissue, and this protein can also be monitored in patients’ serum and help confirm the absence of active disease in GBM." (PMID 36081550, 2022). "In humans, CHI3L1 signaling also plays a critical role in cancer and is increasingly applied as a therapeutic target for various malignancies, including glioma and colon cancer." (PMID 36368330, 2022).
glioma (continued). "Single-cell RNA-seq data led to the unexpected discovery that CHI3L1 was primarily expressed in glioma cells." (PMID 36276655, 2022). "All these suggested self-synthesized CHI3L1 contributed to the NF-κB signaling pathway activation in glioma cells." (PMID 36276655, 2022). "Taken together, CHI3L1 was highly expressed in tumor sites and was significantly correlated with poor survival in patients with glioma." (PMID 36276655, 2022). "We unexpectedly identified two distinct populations of neutrophils at the single-cell level, whose expression of CHI3L1 was second only to CHI3L1high glioma cells." (PMID 36276655, 2022). "Glioma cells with CHI3L1 knockdown also displayed reduced migration capacity, as shown by the wound healing assay." (PMID 36276655, 2022). "The roles of CHI3L1 in glioma proliferation and invasion were investigated in tumor cell lines by gain- and loss- of function, as well as in vivo animal experiments." (PMID 36276655, 2022). "Here, we analyzed the mRNA-seq data from the Gene Expression Omnibus (GEO), The Cancer Genome Atlas (TCGA), and Chinese Glioma Genome Atlas (CGGA) to explore the expression profile of CHI3L1 in glioma at mRNA level." (PMID 36276655, 2022). "MES glioma possessed the highest enrichment score of NF-κB pathway with the highest mRNA expression of CHI3L1." (PMID 36276655, 2022). "Collectively, both the in vivo and in vitro studies indicated that CHI3L1 regulates the proliferation, migration, and survival of glioma cells." (PMID 36276655, 2022). "To gain more insight into the relationship between CHI3L1 expression and glioma phenotype, we extracted mRNA microarray or sequencing cases with detailed clinical information from GEO, TCGA and CGGA databases." (PMID 36276655, 2022). "We elucidated in unprecedented detail how the intracellular and released CHI3L1 played pro-tumor roles in the development of glioma." (PMID 36276655, 2022). "CHI3L1 was over-expressed in tumors compared to normal regions in patients with glioma, and the expression levels of CHI3L1 increased with increasing grades of glioma." (PMID 36276655, 2022). "In conclusion, our findings provided a basis for the potential role of CHI3L1 as a therapeutic target for glioma." (PMID 36276655, 2022). "In conclusion, comprehensive analysis based on transcriptome data suggested that CHI3L1 promoted the activation of the NF-κB pathway to serve as an accomplice during the progression of glioma." (PMID 36276655, 2022). "The mechanisms of how CHI3L1 drives NF-κB pathway activation in glioma and participates in TME reprogramming, including TAMs polarization and angiogenesis warrants further investigation." (PMID 36276655, 2022). "IHC showed that CHI3L1 was enriched in staged gliomas, especially in high grade gliomas (HGG) (WHO III-IV)." (PMID 36276655, 2022). "Altogether, glioma-derived CHI3L1 remodeled the TME into a tumor-promoting and immunosuppressive profile." (PMID 36276655, 2022). "Kaplan-Meier analysis revealed that higher levels of CHI3L1 were associated with worse progression-free survival (PFS) and OS rate in patients with glioma." (PMID 36276655, 2022). "We then explored the roles of CHI3L1 in regulating the expression of immune checkpoints in glioma based on TCGA and CGGA datasets." (PMID 36276655, 2022). "Gliomas of the mesenchymal subtype are defined by high expression of chitinase 3-like 1 and MET5, as well as a high frequency of neurofibromatosis type 1 (NF1) mutation/deletion and low levels of NF1 mRNA." (PMID 34603399, 2021). "Gal-3 also modulates the glioma microenvironment via interaction with the glycoprotein chitinase-3-like 1 (CHI3L1), increasing tumor immunosuppression and promoting macrophage M2-polarization." (PMID 34831271, 2021). "A series of genes such as EN1, S100A4, ANXA1, PDPN, IGFBP2 and CHI3L1 were upregulated in radiotherapy treated glioma patients, while other genes such as PRLHR, SFRP2, BRINP1, TRIM67, LHX5, KCNIP2 and NSG2 were downregulated." (PMID 34852024, 2021).
glioma (continued). "CHI3L1 and NTRK2 were identified as factors that can be associated with IDH1 status and 1p/19q codeletion to distinguish between prognostic groups of glioma from the TCGA cohort." (PMID 34458259, 2021). "It has already been reported that CHI3L1 targeting affords an effective treatment for glioma in animal models." (PMID 30991699, 2019). "CHI3L1 and NTRK2, whose expression is associated with 1p19q co-deletion and IDH status, refined the prognosis of glioma patients, but this should be confirmed by a prospective study." (PMID 30991699, 2019). "In our cohort and the glioma TCGA cohort, low expression of NTRK2 and high expression of CHI3L1 were strongly linked to poor prognosis (p < 0.05)." (PMID 30991699, 2019). "Among these genes, CHI3L1 and NTRK2 were identified as factors that can be associated with IDH status and 1p/19q co-deletion to distinguish between prognostic groups of glioma from the TCGA cohort." (PMID 30991699, 2019). "Since CHI3L1 is implicated as a driver of some aspects of mesenchymal behavior in GBM, our study raises the possibility of a mechanistic link between NF1 and mesenchymal phenotype, mediated in part by CHI3L1 that is produced by the neoplastic glioma cells." (PMID 29643433, 2018). "The mesenchymal subtype in glioma is defined by a genomic and transcriptomic profile, notably by higher expression levels of mesenchymal markers such as CHI3L1/YKL40 and MET." (PMID 30333910, 2018). "CHI3L1 was previously reported in tumour angiogenesis 6, 9, 10, in glioma invasion process 11 and radioresistance." (PMID 27641066, 2017). "To determine the significance of the increased CHI3L1 mRNA expression in glioma, we analyzed the relationship between CHI3L1 mRNA levels and the clinicopathological features of glioma tumor patients." (PMID 27121858, 2016). "Elevated expression of chitinase 3-like 1 (CHI3L1, YKL-40) in glioma was correlated with decreases in disease survival." (PMID 27344170, 2016). "According to the RT-PCR results, “low” mRNA levels of CHI3L1 were determined for 24 (24.5 %), “medium” CHI3L1 levels were determined for 50 (51 %), and “high” CHI3L1 levels were determined for 24 (24.5 %) glioma patients." (PMID 27121858, 2016). "Grade I glioma also showed significantly higher CHI3L1 mRNA expression as compared to grade II and III glioma, but less than GBM." (PMID 27121858, 2016). "Glioma patient with low CHI3L1 mRNA expression had significantly higher chance of longer survival when compared with medium and especially high CHI3L1 expression." (PMID 27121858, 2016). "We analyzed expression of PPIC, EMP3 and CHI3L1 in expression profiles acquired from the Gene Expression Omnibus (GEO) database, and glioma datasets acquired from The Cancer Genome Atlas (TCGA)." (PMID 27801851, 2016). "CHI3L1 suppression by shRNA reduced glioma cell invasion and anchorage-independent growth and increased cell death in response to several anticancer drugs, including cisplatin, etoposide and doxorubicin." (PMID 26425658, 2015). "For example, CHI3L1 regulates the proliferation of glioma cells through MAPK and AKT pathways, and it also plays roles in tumorigenesis and local invasion through matrix metalloproteinase-2." (PMID 26452028, 2015). "Targeting CHI3L1 with neutralizing antibodies has been proven effective as treatment of gliomas in animal models." (PMID 26425658, 2015). "Gliomas, which express CHI3L1, are known to induce local and systemic immunosuppression, inhibiting T-cell-mediated cytotoxic responses to tumor growth." (PMID 26425658, 2015). "In good agreement, CHI3L1 suppression by shRNA reduced glioma cell invasion, anchorage-independent growth and increased cell death in response to several anticancer drugs, including cisplatin, etoposide and doxorubicin." (PMID 26425658, 2015). "In contrast to other cancer types, TNFα suppresses CHI3L1 expression in glioma cell lines in a NF-κB-dependent manner." (PMID 26425658, 2015).
glioma (continued). "Nuclear factor I-X3 and STAT3 has also been identified in controlling the migration and invasion of glioma cells via the regulation of CHI3L1." (PMID 26452028, 2015). "CHI3L1 has been reported to play roles in the carcinogenesis, proliferation, invasion, and metastasis of glioma and prostate cancer." (PMID 26452028, 2015). "Transfection of U87 glioma cells with short-interfering RNAs (siRNAs) targeting all isoforms of VEGF resulted in highest up-regulation of CHI3L1 (YKL-40) and the related CHI3L2 genes." (PMID 24878721, 2014). "CHI3L1 is predominantly expressed in glioma cells and, to a lesser extent, in neutrophils." (PMID 39827337, 2025). "This body of evidence highlights the central role of CHI3L1 in glioma behavior." (PMID 39827337, 2025). "Furthermore, elevated CHI3L1 mRNA expression was observed in gliomas with isocitrate dehydrogenase (IDH) status in wildtype samples, indicating a potential association between CHI3L1 expression and poor clinical outcomes." (PMID 39000203, 2024). "The aberrant expression of CHI3L1 was proved in glioma patients through immunohistochemistry (IHC)." (PMID 39000203, 2024). "Furthermore, the highly expressed CHI3L1 in gliomas enhances NF‐κB signalling by facilitating the translocation of NF‐κB subunits through binding to ACTN4 and NFKB." (PMID 38809929, 2024). "Our hypothesis about the positive role of CHI3L2 in patient prognosis is noteworthy, especially considering that CHI3L1 plays a significant role as a poor prognostic factor in various cancers such as glioma and breast cancer." (PMID 39557919, 2024). "In the context of glioma progression, CHI3L1 is released into the tumor microenvironment and interacts with CD44 expressed on tumor-associated macrophages, thereby activating the downstream PI3K/Akt signaling pathway and contributing to M2 macrophage polarization." (PMID 39068486, 2024). "In this study, we aimed to explore the value of CHI3L1 in predicting tumor progress and uncover the potential mechanisms by which CHI3L1 induces poor outcomes in patients with gliomas, providing guidance for the development of targeted treatments in the future." (PMID 39000203, 2024). "Notably, CHI3L1 has received growing research interest as a novel prognostic marker for high-grade gliomas." (PMID 38275876, 2024). "We observed that the expression of CHI3L1 was consistently upregulated in various solid tumors, contributing to poor clinical outcomes, indicating its distinctive role in tumor progression, particularly in gliomas." (PMID 39000203, 2024). "Additionally, we are planning to set up a multicenter study to investigate the correlation between EMP3 and CHI3L1 expression levels and survival outcomes in glioma patients." (PMID 37887529, 2023). "We speculate that targeted inhibitors of EMP3 and CHI3L1 genes may be an effective method to improve the prognosis of glioma patients in the future." (PMID 37887529, 2023). "Previous studies have shown that EMP3 and CHI3L1 are upregulated in glioma tissues." (PMID 37887529, 2023). "Therefore, we believe that the expression level of EMP3 and CHI3L1 have guiding significance for the prognosis and survival of patients with low-grade glioma." (PMID 37887529, 2023). "Moreover, in this study, we conducted statistical analyses on the role of EMP3 and CHI3L1 in glioma from existing public data and verified the results with a simple qRT-PCR validation in human specimens." (PMID 37887529, 2023). "Our study confirmed a correlation between EMP3 and CHI3L1 in glioma cells." (PMID 37887529, 2023). "Previous studies have separately investigated the roles of EMP3 and CHI3L1 in gliomas." (PMID 37887529, 2023). "The results showed that EMP3 and CHI3L1 had a specific correlation with the prediction of glioma and could be used as a combined index to judge the prognosis of glioma patients." (PMID 37887529, 2023).
glioma (continued). "The previous study has also demonstrated that CHI3L1 could promote the expression of PD‐L1, which further proved the immunosuppressive role of HA in the tumor microenvironment of gliomas." (PMID 36134697, 2022). "Surprisingly, CHI3L1 was preferentially expressed in glioma cells, followed by neutrophils." (PMID 36276655, 2022). "We also observed a positive correlation between CHI3L1 expression and NF-κB signaling pathway activation at single-cell level, which implied that CHI3L1 played an indispensable role in the activation of the NF-κB signaling pathway in glioma." (PMID 36276655, 2022). "Increased infiltration of neutrophils in the TME is also positively correlated with increasing glioma malignancy 46, which may result from the overexpression of CHI3L1 to some extent." (PMID 36276655, 2022). "Moreover, the serum levels of CHI3L1 in patients with glioma were higher than those of healthy controls detected by ELISA." (PMID 36276655, 2022). "CHI3L1 was primarily expressed in glioma cells, followed by neutrophils." (PMID 36276655, 2022). "Moreover, we performed IF staining on frozen sections of intratumor and paired peritumor tissues, and confirmed a positive correlation between CHI3L1 and NF-κB p65 expression in glioma." (PMID 36276655, 2022). "Next, we investigated how CHI3L1 was secreted by glioma cells into the extracellular space." (PMID 36276655, 2022). "Collectively, CHI3L1 altered the phenotypes and proportions of immune cells to rebuild an immunosuppressive and tumor-promoting microenvironment during the progression of glioma." (PMID 36276655, 2022). "We identified two distinct sub-populations of glioma cells with high and low expression of CHI3L1." (PMID 36276655, 2022). "Interestingly, CHI3L1-based targeted therapy has been increasingly applied to the treatment of tumors including glioma and colon cancer as well as rheumatoid arthritis." (PMID 32929074, 2020). "CHI3L1 can be associated with IDH status and 1p/19q co-deletion in patients with glioma." (PMID 32725165, 2020). "After intersecting DEPGs generated from the two datasets, three common DEPGs (PPIC, EMP3 and CHI3L1) were identified, suggesting that these genes may be potential predictors of prognosis in high-grade gliomas patients." (PMID 27801851, 2016). "We propose CHI3L1 mRNA expression as a prognostic biomarker for patients with glioma." (PMID 27121858, 2016). "This demonstrates that CHI3L1 mRNA expression level could be informative prognostic marker for glioma patient overall survival." (PMID 27121858, 2016). "It is important to mention that grade I glioma expression profile was more similar to healthy brain (RHB) sample and this could indicate that expression of CHI3L1 is at very beginning stage of alteration in grade I glioma." (PMID 27121858, 2016). "Besides that, CHI3L1 mRNA expression in glioma grade I also showed to be significant higher than compared with grade II and III, respectively p < 0.001 and p = 0.032." (PMID 27121858, 2016). "We determined that PPIC, EMP3 and CHI3L1 were up-regulated in the glioma tissue." (PMID 27801851, 2016). "Intersection of the DEPGs revealed a total of three common DEPGs—PPIC, EMP3 and CHI3L1—suggesting that these common DEPGs may be potential prognostic indicators of glioma progression." (PMID 27801851, 2016). "Taken together, the results suggest that expressions of PPIC, EMP3 and CHI3L1 may play a vital role in glioma progression." (PMID 27801851, 2016). "Also, resveratrol was found to repress the expression of CHI3L1 in glioma cells in in vitro experiments." (PMID 26452028, 2015). "Even though TNF-alpha causes recruitment of p65 and p50 subunits of NF-κB to the CHI3L1 promoter in all cell types, recruitment of histone deacetylases (HDAC)-1 and -2, and a consequent deacetylation of histone H3 at the CHI3L1 promoter occurs only in glioma cells." (PMID 26425658, 2015).